OR14L1 (olfactory receptor family 14 subfamily L member 1)
Description:
Odorant receptor.
Synonyms: OR14L1P; OR5AV1P; OR1-35; OR1-36; OR5AV1
Tractability: Antibody: UniProt places it where antibodies can reach, with high confidence; UniProt predicts a signal peptide or a membrane-spanning region; its Gene Ontology location is reachable by antibodies, with medium confidence.
Gene: Protein-coding gene on chromosome 1 (247,617,143 to 247,622,372, forward strand). Ensembl gene ENSG00000198452.
Subcellular location: Cell membrane
Gene Ontology:
Molecular function: odorant binding; olfactory receptor activity; G protein-coupled receptor activity
Biological process: sensory perception of smell; detection of chemical stimulus involved in sensory perception of smell; G protein-coupled receptor signaling pathway
Cellular component: plasma membrane; membrane
Homologues: Orthologues: guinea pig OR14L1 (67% identical). Paralogues in human: OR14A2 (49% identical), OR14A16 (48% identical), OR14J1 (47% identical), OR14K1 (46% identical), OR14I1 (44% identical), OR14C36 (43% identical), OR5AP2 (40% identical), OR8K3 (40% identical), OR5AR1 (40% identical), OR5B21 (39% identical), OR5I1 (39% identical), OR9H1 (39% identical), and 84 more.